AR (androgen receptor)
Diseases named in the same sentence as AR in open-access papers (continued):
Sharing a sentence is not in itself a finding about the gene and the disease.
tumor (continued). "Future studies should focus on assessing longitudinal changes in tumor microenvironment, biomarkers of prognosis, androgen receptor expression, tumor driver expression, and immune infiltrate levels before and after treatment." (PMID 40177247, 2025). "They attributed these effects to AR activation, the suppression of ER-regulated cell cycle genes, and the upregulation of AR target genes, including tumor suppressors." (PMID 40870508, 2025). "Early preclinical data indicate that PROTAC-mediated AR degradation not only reduces tumor growth but also enhances anti-tumor immunity." (PMID 40940929, 2025). "These metabolites modulate host clock genes (BMAL1, PER1/2), oxidative stress, and nuclear receptor pathways (PPARγ, FXR), influencing androgen receptor activity and tumor metabolism (R10)." (PMID 41384118, 2025). "In PCa cells, unmutated SPOP promotes the degradation of full-length wild-type AR (AR-WT), and acts as a tumor suppressor." (PMID 37847340, 2024). "As expected from its wide expression in normal tissue (proteinatlas.org, accessed on 28 December 2023), various different tumor types can express AR." (PMID 38790919, 2024). "During disease progression, however, the tumor cells eventually differ in their androgen sensitivity and AR dependency." (PMID 39768760, 2024). "In most AR antagonist-resistant tumors, the AR signaling is still active, promoting tumor growth and progression." (PMID 38675453, 2024). "A more immunosuppressive TIME with a predominance of innate immune cells and lower levels of tumor-infiltrating lymphocytes (TILs) was observed in luminal androgen receptor (LAR) tumors." (PMID 38893213, 2024). "Conversely, the knockdown of LINC01126 impeded the growth of C4‐2B tumours in castrated conditions by repressing AR signalling." (PMID 38214432, 2024). "AR activation has been described as essential for the ability to induce tumor cell death by TAMs, which is why ADT would be counterproductive to the local innate immune response." (PMID 38396837, 2024). "This uncovered a select cohort of AR positive (ARPC) mCRPC patients whose tumours were both highly (MitoShigh) and moderately (MitoSmed) enriched for the MitoS gene signature." (PMID 39025852, 2024). "Given AhR's ability to modulate AR signaling bidirectionally and its independent effects on gene transcription and tumor cell proliferation, it holds potential as both a therapeutic target and a biomarker for disease aggressiveness." (PMID 39184676, 2024). "Even though patient’s stratification for AR-targeted therapy is usually based on AR status of tumor tissue, efforts have been made to examine AR status using liquid biopsies." (PMID 37902839, 2024). "In PCa, AR and its signaling pathways are responsible for the growth, proliferation, and survival of tumor cells during the androgen-dependent stage, and activating mutations in AR are involved in the development and progression of the disease." (PMID 39594771, 2024). "Circulating tumor DNA testing at the onset of the second episode of DIC revealed high levels of androgen receptor, CCND1, and PDGFRA gene amplification." (PMID 39764338, 2024). "In tumor samples harvested from lead-challenged cells, both ERα and AR were detected by qPCR, yet there was a significant decrease in AR seen in lead-challenged tumor cells from male mice only." (PMID 38892327, 2024). "Oral administration of ARD-2585 effectively reduced AR protein expression and inhibited growth in VCaP tumor tissues that had been transplanted into mice." (PMID 37847340, 2024). "Our findings support the concept that androgen/AR reduces global fucosylation levels by transcriptionally downregulating FUK while tilting its function toward tumor promotion by upregulating FUT4 expression." (PMID 38326303, 2024). "These mutations also prevent the breakdown of androgen receptor proteins, boosting AR signaling and thereby fostering tumor growth." (PMID 39296545, 2024).
tumor (continued). "Primary tumors of LNCaP spheroids evolved earlier, exhibiting a shorter tumor doubling time whilst developing larger tumor volumes, which was reflected by a higher immunohistochemical expression of Ki-67 and AR, too." (PMID 38632341, 2024). "Approximately 20% of patients with CRPC have X chromosome rearrangement and subsequent AR amplification, resulting in increased levels of AR proteins in tumor cells." (PMID 39770431, 2024). "Patients with PC, they have certain mechanisms of therapy resistance, such as AR overexpression, like tumor cell survival and proliferation." (PMID 39351434, 2024). "Fully in line with this, our PCABM predicts that ADT affects the cellular behavior of both tumor cells and M1 macrophages, further solidifying our observation that AR plays an immunomodulatory role in the prostate TME." (PMID 38383542, 2024). "The tumor cells downregulated androgen receptor (AR) expression and induced CAF biomarkers in stromal fibroblasts." (PMID 39459070, 2024). "EPI-001 and EPI analogs covalently bound to the NTD, effectively blocking AR and its splice variant’s (ARv567es) transcriptional activity, and showed reduced CRPC tumor growth in experiments." (PMID 38201308, 2024). "Of note, AR-V7-positive status did correlate with higher levels of AR, a higher tumor load, and increased PSMA expression in patients." (PMID 38201308, 2024). "According to our current study, these residual androgen in tumor microenvironment can promote metastasis of AR‐positive PCa cells." (PMID 39149855, 2024). "Our analysis of 141 different tumor types for AR immunostaining provides a comprehensive overview on AR in human tumors and identifies AR expression in many “hormone-dependent” and “hormone-independent” tumor types." (PMID 38790919, 2024). "The activation of AR increases the expression of downstream targets like cyclin D1, which drives cell cycle progression and tumor growth." (PMID 39725665, 2024). "Nearly 90% of ER-positive tumours express AR, but less than 30% of ER-negative breast cancers are AR positive." (PMID 38228924, 2024). "These genetic variations can lead to higher circulating levels of testosterone and dihydrotestosterone (DHT), further enhancing AR activity and promoting tumor growth." (PMID 39600743, 2024). "This fact is in line with other authors that showed the relation between AR and ERβ expression and tumor development." (PMID 38338747, 2024). "Androgen independence can arise in PCa subtypes within the primary tumor that are indifferent to ADT or other androgen receptor signaling inhibitors, thus mimicking castration resistance." (PMID 40129601, 2024). "Recent studies analyzing the molecular and histologic profiles of SDC indicate that the androgen receptor (AR) signaling pathway plays a role in tumor progression and aggressiveness." (PMID 39518333, 2024). "Despite of the initial response, ADT treatment will lead to the emergence of recurrent tumor, suggesting other signaling pathways actively respond in order to bypass AR inhibition." (PMID 39268470, 2024). "HOXB13 has been shown to act as a tumour suppressor in PCa through the inhibition of AR activity, thus functioning as an AR repressor and exerting a growth-inhibiting effect on PCa cells." (PMID 39682746, 2024). "Studies using acetylation-defective K618R and acetylation-mimicking K618Q mutants demonstrated that K618 acetylation promotes RNA Pol II binding, AR transcriptional activity, PCa cell growth, and xenograft tumor formation." (PMID 38275816, 2024). "Our study has identified, in addition to systemic levels of testosterone, tumor-specific AR and its fucosylation signaling effectors (FUT4, fucosylated-L1CAM, and AJs), as potential risk factors for disease progression and as promising prognostic biomarkers." (PMID 38326303, 2024).
tumor (continued). "Given that PyMT lung metastases retain AR expression, the hormonal environment of male mice likely mediates neutrophil accumulation in the lungs that supports accelerated secondary tumor propagation." (PMID 39684829, 2024). "This inherent cancer cell heterogeneity contributes to tumor resistance to clinical treatment, especially the molecularly targeted therapies such as tyrosine kinase inhibitors (TKIs) and androgen receptor signaling inhibitors (ARSIs)." (PMID 39363904, 2024). "Cdk12 is a tumor suppressor gene responsible for mitigating AR/Myc hypertranscription and TRC-mediated DNA damage." (PMID 39368479, 2024). "A significant inhibitory effect of Selinexor on AR-dependent and -independent PCa tumor growth was observed both in vivo and ex vivo, suggesting that XPO1 blockade can repress both AR and other oncogenic pathway-mediated PCa growth." (PMID 38336745, 2024). "DPYSL5, NCAM, CGA, SYP and AR protein expressions were evaluated in the tumor tissue samples using immunohistochemistry (IHC)." (PMID 38238517, 2024). "In this subgroup, AR behaves as an oncogenic driver for tumor cell proliferation, and tumors have a high expression of FOXA1, XBP1, and KRT18." (PMID 38339092, 2024). "Here, we report that KHSRP acetylation, a new post‐translational modification of KHSRP, is tightly associated with AR activity and DDR regulation, which serves tumor growth and malignancy by impairing DDR‐related mRNA decay in PCa." (PMID 38501452, 2024). "In this study, the intestinal barrier damage after ADT led to LPS entry into the circulation, LPS translocation to tumor stimulated NF-κB phosphorylation, and upregulation of AR, ultimately promoting the progression of CRPC." (PMID 39203495, 2024). "mCSPC treatment aims to prolong survival through long-term tumor suppression by targeting tumor proliferation, particularly the androgen receptor (AR) pathway." (PMID 39335158, 2024). "In TNBC and HER2 + BC, AR expression increased tumor proliferation, while in ERα-positive BC, its role is ambiguous with either pro- or anti-proliferative effects, depending on the level of co-expressed ERα and the presence of the particular ligand." (PMID 37902839, 2024). "The results further supported that LINC01126 contributed to tumour growth by reactivating AR signalling after castration, which is widely accepted as a primary mechanism for CRPC formation." (PMID 38214432, 2024). "Activation of AhR with certain ligands has been shown to enhance AR-mediated transcription and promote tumor cell proliferation." (PMID 39184676, 2024). "In the early observations, AR was overexpressed in 60–80% of human HCCs, not only in the tumor but also in the peritumor liver tissue." (PMID 39061609, 2024). "AR expression was highest in tumor-adjacent endometrium and lowest in high-grade tumors, G3 EEC and USC." (PMID 39205690, 2024). "The [225Ac]Ac-hu11B6 therapy took advantage of the unique phenomenon of increasing expression of AR and hK2 from alpha particle-induced DNA damage in the LNCaP-AR tumor model." (PMID 38773983, 2024). "Our data supports a more complicated role of miR-1271–5p across PCa, depending on tumour stage, from AR dependence to castrate resistance." (PMID 39267821, 2024). "The aim of this study was to determine the AR expression on disseminated tumor cells (DTCs) as a surrogate marker of minimal residual disease (MRD) and potential precursor of metastasis in early BC." (PMID 37902839, 2024). "[18F]FDG uptake correlates with tumor aggressiveness and sensitivity to targeted therapies, such as AR inhibitors and immunotherapy." (PMID 39110196, 2024). "LNCaP is a EA cell line that was derived from a metastatic lymph node lesion of PCa that was AR positive, exhibiting androgen-sensitive tumor growth." (PMID 38792011, 2024). "The first-generation antiandrogen bicalutamide inhibited the DHT-induced tumor growth of AR-positive TNBC human MDA-MB-453 xenografts in mice." (PMID 38339092, 2024).
tumor (continued). "mCRPC: metastatic castration-resistant prostate cancer; AR: androgen receptor; AR-V7: AR splice variant 7; PSMA: prostate-specific membrane antigen; PSA: prostate-specific antigen; CTCs: circulating tumor cells; cfRNA: cell-free RNA." (PMID 38627648, 2024). "This raises an intriguing possibility for the AR transcriptional activity stemming from a subset of canonical elements to rather impede tumor formation and/or progression, which is consistent with the physiological role of AR as a prodifferentiation factor." (PMID 39251788, 2024). "Our highly standardized analysis of 18,234 tumors from 141 human tumor types and subtypes has resulted in a ranking order according to the prevalence of AR expression." (PMID 38790919, 2024). "A recent study demonstrated that targeting androgen receptor (AR) to reduce PD-L1 expression can enhance the tumor-killing abilities of NK cells." (PMID 38400838, 2024). "To determine if AR mutation plays a role in HCC, we analyzed a transcriptome dataset of TCGA database, comprising 366 primary HCC tumor samples." (PMID 38182647, 2024). "Another significant study provided evidence that AhR activation with specific ligands increases AR transcriptional activity, leading to enhanced tumor cell proliferation." (PMID 39184676, 2024). "For example, up to 50% of AR mutations in CRPC strains, such as residue 741 (W741C), can convert the AR antagonist bicalutamide to an activator that activates the AR and promotes tumor growth." (PMID 39011396, 2024). "Both studies serve as valuable supplements to one another and offer potential directions for future research in AR’s critical role as a regulator of tumor immunity." (PMID 38491510, 2024). "Given a low overall concordance of AR expression in PT and metastasis, it is reasonable to assess the AR status on all available tumor specimens, before recommending anti-AR therapy." (PMID 37902839, 2024). "70.5% of patients showed AR staining in > 70% of tumor cells and/or HER2 positivity and therefore at least one molecular target." (PMID 38587651, 2024). "HE3235 significantly decelerated tumor growth, decreased AR expression, lowered intratumoral testosterone and DHT levels, and inhibited the development of bone tumors." (PMID 39200101, 2024). "As such, the implications of the AR and Gli1 interactions through stromal and epithelial cells in both normal and tumor status should be further investigated." (PMID 39369165, 2024). "Nuclear AR staining in > 70% of tumor cells was found in 56.8% and HER2 positivity (IHC 3 +) in 36.4% of cases." (PMID 38587651, 2024). "These aberrations will increase during tumor progression; therefore, alterations in the AR pathway can be used as prognostic biomarkers for PCa." (PMID 40353136, 2024). "We then explored the potential role of MPC2 in supporting AR-driven tumour reprogramming towards a lipogenic phenotype, by measuring the expression of both AR and FASN in our samples." (PMID 39013948, 2024). "The tumor cells expressed estrogen receptor (ER) at 60%, progesterone receptor (PR) at 5%, and androgen receptor (AR) at 80%, a Her-2/neu score of 1+ and negative for CK5/6." (PMID 38611678, 2024). "The expression of SIRT2 in CRPC leads to unchecked p300 activity, which drives transcriptional programs promoting tumor aggression and resistance to androgen receptor signaling inhibitors (ARSIs)." (PMID 39796040, 2024). "A number of oncogenes and tumor suppressors have been observed leveraging PTMs to influence AR activity." (PMID 38275816, 2024). "Among the established spheroid models, most of the tumor spheroids expressed high levels of AR, CK8, and AMACR proteins, similar to their parental PCa cells." (PMID 38256166, 2024). "SIRT3 and SIRT4 suppress oncogenic pathways by regulating cancer metabolism, while SIRT2 and SIRT6 influence tumor aggressiveness and androgen receptor sensitivity, with SIRT6 promoting metastatic potential." (PMID 39796040, 2024).
tumor (continued). "AR expression is higher in the enhancing tumor periphery and peritumoral areas compared to the tumor core." (PMID 39768232, 2024). "As the majority of mCRPC cases retain a high dependency on AR signaling, new-generation hormonal agents, through deeper AR pathway inhibition, effectively suppress tumor growth even in the castration-resistant setting." (PMID 39195285, 2024). "HOXB13 and FOXA1 are enriched at tumor-promoting genes and can open the chromatin to generate a permissive chromatin landscape to support AR activities in androgen-dependent and independent states." (PMID 38201640, 2024). "GP96 and AR expression were immunohistochemically evaluated on tissue microarrays constructed from two 2 mm diameter cores of formalin-fixed paraffin-embedded tumor tissues from each patient." (PMID 39768587, 2024). "A meta-analysis of 1447 patients indicated that AR expression is 28.2% and correlated with low tumor grade and stage." (PMID 38892327, 2024). "We have recently updated this prognostic model to include molecular variables such as the presence of circulating tumor cells (CTCs) and the amplification of the androgen receptor (AR) in circulating plasma DNA." (PMID 39061175, 2024). "The defining feature of the LAR subtype is the expression of the androgen receptor (AR) in the tumor cells." (PMID 39272660, 2024). "Conversely, AhR can also inhibit AR signaling by recruiting corepressors or promoting AR degradation, thus suppressing tumor growth." (PMID 39184676, 2024). "Here, we show that the tumor-specific enhancer circuitry of AR is critically reliant on the activity of Nuclear Receptor Binding SET Domain Protein 2 (NSD2), a histone 3 lysine 36 di-methyltransferase." (PMID 38464251, 2024). "Here, we found the overexpression of FOXA1 and HOXB13 alone, or in combination, to markedly shift the AR cistrome away from full AREs (normal-like) towards chimeric AR half elements in the tumor-like state." (PMID 39251788, 2024). "High doses of 8β-VE2 induced apoptosis in the PCa cell lines and the prostate of rodent tumor models, which was related to the interference in androgen/AR signaling." (PMID 39200101, 2024). "Regarding mitochondrial dynamics, patients with higher mtPCDI exhibit increased AR activity and higher tumor cell stemness scores, which are indicative of aggressive cancer traits." (PMID 39296545, 2024). "The anti-tumor drug enzalutamide inhibits PEX10 by inhibiting the function of AR, and synergize with ROS activators ML210 or RSL3 to produce a stronger anti-tumor effect, thereby sensitizing cells to ROS activators." (PMID 39097593, 2024). "As shown inFig 4C and4D,PCA3, an established PCa marker, was highly expressed in the LE_AR_lo subtype, so we assigned LE_AR_lo as tumor cells but LE-AR-hi as normal luminal cells." (PMID 38808547, 2024). "Intriguingly, these data reflect a heterogeneous metastatic landscape comprised of pockets of tumor cells that exhibit higher AR activity than AR+ populations within primary sites." (PMID 38326303, 2024). "AR inhibition from darolutamide increased the PSMA expression thereby increasing the tumor-targeted delivery of PSMA-TTC and the therapeutic response." (PMID 38773983, 2024). "Targeting of 6PGD was associated with two important tumour-suppressive mechanisms: firstly, it increased the activity of the AMP-activated protein kinase (AMPK); secondly, it enhanced AR ubiquitylation, leading to a reduction in AR protein levels and activity." (PMID 38969865, 2024). "This combined treatment achieved dual inhibition of AR and cell mitosis, significantly inhibiting tumor growth and restoring sensitivity to enzalutamide in PCa." (PMID 38898473, 2024). "CDK9 inhibition can also decrease phosphorylation of the androgen receptor (AR), decreasing AR-dependent transcription and reducing tumor burden in vivo." (PMID 38172923, 2024).